ZC3H12A (zinc finger CCCH-type containing 12A)
Description:
Endoribonuclease involved in various biological functions such as cellular inflammatory response and immune homeostasis, glial differentiation of neuroprogenitor cells, cell death of cardiomyocytes, adipogenesis and angiogenesis. Functions as an endoribonuclease involved in mRNA decay. Modulates the inflammatory response by promoting the degradation of a set of translationally active cytokine-induced inflammation-related mRNAs, such as IL6 and IL12B, during the early phase of inflammation. Prevents aberrant T-cell-mediated immune reaction by degradation of multiple mRNAs controlling T-cell activation, such as those encoding cytokines (IL6 and IL2), cell surface receptors (ICOS, TNFRSF4 and TNFR2) and transcription factor (REL) (By similarity). Inhibits cooperatively with ZC3H12A the differentiation of helper T cells Th17 in lungs. They repress target mRNA encoding the Th17 cell-promoting factors IL6, ICOS, REL, IRF4, NFKBID and NFKBIZ. The cooperation requires RNA-binding by RC3H1 and the nuclease activity of ZC3H12A (By similarity). Together with RC3H1, destabilizes TNFRSF4/OX40 mRNA by binding to the conserved stem loop structure in its 3'UTR (By similarity). Self regulates by destabilizing its own mRNA (By similarity). Cleaves mRNA harboring a stem-loop (SL), often located in their 3'-UTRs, during the early phase of inflammation in a helicase UPF1-dependent manner. Plays a role in the inhibition of microRNAs (miRNAs) biogenesis. Cleaves the terminal loop of a set of precursor miRNAs (pre-miRNAs) important for the regulation of the inflammatory response leading to their degradation, and thus preventing the biosynthesis of mature miRNAs. Also plays a role in promoting angiogenesis in response to inflammatory cytokines by inhibiting the production of antiangiogenic microRNAs via its anti-dicer RNase activity. Affects the overall ubiquitination of cellular proteins (By similarity). Positively regulates deubiquitinase activity promoting the cleavage at 'Lys-48'- and 'Lys-63'-linked polyubiquitin chains on TNF receptor-associated factors (TRAFs), preventing JNK and NF-kappa-B signaling pathway activation, and hence negatively regulating macrophage-mediated inflammatory response and immune homeostasis (By similarity). Also induces deubiquitination of the transcription factor HIF1A, probably leading to its stabilization and nuclear import, thereby positively regulating the expression of proangiogenic HIF1A-targeted genes. Involved in a TANK-dependent negative feedback response to attenuate NF-kappaB activation through the deubiquitination of IKBKG or TRAF6 in response to interleukin-1-beta (IL1B) stimulation or upon DNA damage. Prevents stress granule (SGs) formation and promotes macrophage apoptosis under stress conditions, including arsenite-induced oxidative stress, heat shock and energy deprivation (By similarity). Plays a role in the regulation of macrophage polarization; promotes IL4-induced polarization of macrophages M1 into anti-inflammatory M2 state (By similarity). May also act as a transcription factor that regulates the expression of multiple genes involved in inflammatory response, angiogenesis, adipogenesis and apoptosis. Functions as a positive regulator of glial differentiation of neuroprogenitor cells through an amyloid precursor protein (APP)-dependent signaling pathway. Attenuates septic myocardial contractile dysfunction in response to lipopolysaccharide (LPS) by reducing I-kappa-B-kinase (IKK)-mediated NF-kappa-B activation, and hence myocardial pro-inflammatory cytokine production (By similarity). (Microbial infection) Binds to Japanese encephalitis virus (JEV) and Dengue virus (DEN) RNAs. (Microbial infection) Exhibits antiviral activity against HIV-1 in lymphocytes by decreasing the abundance of HIV-1 viral RNA species.
Synonyms: MCPIP-1; Reg1; MCPIP; MCPIP1; FLJ23231; Regnase-1; dJ423B22.1
Tractability: Antibody: UniProt places it where antibodies can reach, with medium confidence. PROTAC: UniProt records ubiquitination sites on it; ubiquitination databases record sites on it.
Gene: Protein-coding gene on chromosome 1 (37,474,496 to 37,484,379, forward strand). Ensembl gene ENSG00000163874.
Subcellular location: Nucleus; Cytoplasm; Cytoplasm, P-body; Rough endoplasmic reticulum membrane; Cytoplasmic granule
Subcellular location (Human Protein Atlas): Cytoplasmic bodies; Nucleoplasm
Pathways (Reactome):
Cell-Cell communication: Regulation of CDH19 Expression and Function
Gene Ontology:
Molecular function: chromatin binding; cysteine-type deubiquitinase activity; DNA binding; miRNA binding; mRNA binding; protein binding; RNA binding; RNA nuclease activity; mRNA 3'-UTR AU-rich region binding; mRNA 3'-UTR binding; ribosome binding; RNA endonuclease activity; RNA exonuclease activity; RNA stem-loop binding; nuclease activity
Biological process: 3'-UTR-mediated mRNA destabilization; cellular response to chemokine; cellular response to lipopolysaccharide; cellular response to tumor necrosis factor; cellular response to virus; DNA damage response; host-mediated suppression of viral genome replication; immune response-activating signaling pathway; miRNA catabolic process; negative regulation of canonical NF-kappaB signal transduction; negative regulation of interleukin-6 production; negative regulation of macrophage activation; negative regulation of nitric oxide biosynthetic process; negative regulation of transcription by RNA polymerase II; negative regulation of tumor necrosis factor production; positive regulation of angiogenesis; positive regulation of autophagy; positive regulation of defense response to virus by host; positive regulation of endothelial cell migration; positive regulation of fat cell differentiation; positive regulation of gene expression; positive regulation of lipid storage; positive regulation of miRNA catabolic process; positive regulation of mRNA catabolic process; positive regulation of p38MAPK cascade; and 25 more
Cellular component: cytoplasm; cytoplasmic ribonucleoprotein granule; cytoskeleton; nucleoplasm; nucleus; P-body; protein-containing complex; rough endoplasmic reticulum membrane; rough endoplasmic reticulum
Genetic constraint (gnomAD): Loss-of-function variants: 9 observed, 35.74 expected, observed/expected ratio (o/e) 0.25, 90% interval 0.15 to 0.44. The upper end of that interval is the gene's LOEUF score, 0.44, which puts it in group 1 of 6, group 1 being the genes least tolerant of losing a copy. Missense variants: 617 observed, 830.93 expected, observed/expected ratio (o/e) 0.74, 90% interval 0.69 to 0.79. Synonymous variants: 323 observed, 351.62 expected, observed/expected ratio (o/e) 0.92, 90% interval 0.84 to 1.01.
Homologues: Orthologues: chimpanzee ZC3H12A (99% identical), macaque ZC3H12A (97% identical), pig ZC3H12A (84% identical), rat Zc3h12a (83% identical), mouse Zc3h12a (82% identical), guinea pig ZC3H12A (80% identical), dog ZC3H12A (80% identical), rabbit ZC3H12A (74% identical), tropical clawed frog zc3h12a (48% identical), zebrafish zc3h12aa (35% identical), Drosophila melanogaster Regnase-1 (31% identical), Caenorhabditis elegans rege-1 (30% identical), and 4 more. Paralogues in human: ZC3H12C (47% identical), ZC3H12B (45% identical), ZC3H12D (36% identical), N4BP1 (22% identical), NYNRIN (21% identical), KHNYN (20% identical).
Diseases named in the same sentence as ZC3H12A in open-access papers:
ZC3H12A is named in the same sentence as 158 diseases in open-access papers, as found by Europe PMC text mining. Sharing a sentence is not in itself a finding about the gene and the disease. The quoted sentences say what the papers report.
breast carcinoma (15 papers, 2017 to 2025). "A positive correlation between TARBP2 and ZC3H12A (r = −0.19, p < 0.0001) was also observed in human breast cancer tissues." (PMID 35008634, 2021). "ZC3H12A has been shown to induce apoptosis in breast cancer cells by degrading the mRNA of anti- apoptotic genes through binding to a stem-loop structure in the 3’UTR of target transcripts." (PMID 31106233, 2019). "It was previously reported that ZC3H12A expression was correlated with tumor grade and patient survival in clear cell renal cell carcinoma and breast cancer." (PMID 31106233, 2019). "However, the Kaplan–Meier (KM) plot analysis revealed that ZC3H12A is a favorable marker for the prognosis of patients with breast cancer, which may counteract the mechanism of TARBP2-mediated deubiquitination of HIF-1α." (PMID 35008634, 2021).
autoimmune disease (10 papers, 2015 to 2025). A disorder resulting from loss of function or tissue destruction of an organ or multiple organs, arising from humoral or cellular immune responses of the individual to their own tissue constituents. "However, recent research has been delving into the central role of ZC3H12A within complex disease networks—such as cancer, autoimmune diseases, and viral infections—while exploring its translational potential as a therapeutic target." (PMID 41154702, 2025).
renal carcinoma (7 papers, 2017 to 2025). A carcinoma arising from the epithelium of the renal parenchyma or the renal pelvis. "Different from breast or renal cancer, ZC3H12A less likely induces apoptosis or inhibits angiogenesis in CRC indicated by expression correlation of ZC3H12A mRNA with those processes- related genes." (PMID 31106233, 2019). "A recent study supports a coordinate regulation of ZC3H12A/MCPIP1 and CDKN1A/p21 in a human renal carcinoma cell line." (PMID 32615986, 2020). "Several studies showed that CDKN1A/p21 is expressed at high levels ex vivo in cells from individuals who naturally control HIV-1 replication (HIC) and a recent study supports a coordinate regulation of ZC3H12A/MCPIP1 and CDKN1A/p21 transcripts in a model of renal carcinoma cells." (PMID 32615986, 2020).
viral infection (7 papers, 2016 to 2025). "Additionally, autophagy genes IFI16, ZC3H12A, SQSTM1, WDR81, and PIK3R2 are associated with viral infection, including SARS-CoV-1 and were downregulated in this study when cells were treated with NIC." (PMID 37901834, 2023).
colon cancer (6 papers, 2013 to 2022). "Prior studies found ZC3H12A has links with immune homeostasis and post-transcriptional regulation which can stimulate tumor progression in lung and colon cancer." (PMID 36419007, 2022). "Recently, ZC3H12A has been identified as one of the upregulated genes in S100A8/A9-activated colon tumor cells, whose products promote leukocyte recruitment, angiogenesis, tumor migration, wound healing, and formation of premetastatic niches in distal metastatic organs." (PMID 23658834, 2013).
colorectal cancer (6 papers, 2016 to 2025). A primary or metastatic malignant neoplasm that affects the colon or rectum. "In contrast, the tumor-suppressing function of ZC3H12A in colorectal cancer (CRC) exhibits a more complex hierarchy." (PMID 41154702, 2025). "Previous studies have also shown that downregulation of ZC3H12A can augment the aggressive features of tumor and serves as a contributing factor to the decline in disease-free survival of colorectal cancer patients." (PMID 33718596, 2021). "Clinical significance of ZC3H12A in colorectal cancer specimens from the TCGA, GSE14333, and Shanghai databases." (PMID 31106233, 2019). "Whether driving immune evasion in pancreatic and gastric cancers or mediating cross-talk between epithelial self-defense and microenvironmental signals in colorectal cancer, ZC3H12A inactivation consistently propels more malignant tumor phenotypes." (PMID 41154702, 2025).
psoriasis (6 papers, 2017 to 2021). An autoimmune condition characterized by red, well-delineated plaques with silvery scales that are usually on the extensor surfaces and scalp. "We thus examined genes elevated in psoriasis lesions and induced in human KCs following treatment with poly(I:C) (e.g., Ehf, Nfkbiz, Zc3h12a)." (PMID 28279190, 2017).
gastric cancer (4 papers, 2013 to 2025). A primary or metastatic malignant neoplasm involving the stomach. "It was discovered that upregulated ATP2B1-AS1 or silenced miR-425-3p prevents gastric cancer cells from escaping the immune system by increasing ZC3H12A levels." (PMID 36793271, 2023).
pulmonary fibrosis (4 papers, 2016 to 2024). Chronic progressive interstitial lung disorder characterized by the replacement of the lung tissue by connective tissue, leading to progressive dyspnea, respiratory failure, or right heart failure. "MCPIP1 (also known as ZC3H12A) is involved in silica-induced pulmonary fibrosis and regulates macrophage and fibroblast activation." (PMID 35216634, 2022). "Accordingly, both ZC3H12A and ZC3H4 are involved in the progression of pulmonary fibrosis, but the connection to anoikis is still unclear." (PMID 35216634, 2022).
glioblastoma (3 papers, 2020 to 2026). The most malignant astrocytic tumor (WHO grade IV). "Survival analysis revealed eight RBPs (PTRF, FNDC3B, SLC25A43, ZC3H12A, LRRFIP1, HSP90B1, HSPA5, and BNC2) are significantly associated with the survival of glioblastoma patients." (PMID 32272554, 2020).
ischemic heart disease (3 papers, 2008 to 2025). "Zc3h12a (also designated as MCPIP) was significantly increased in ischemic heart and promoted cell apoptosis, and mediated MCP-1 induced angiogenesis, suggesting that it may be an important player in human ischemic heart disease." (PMID 18682727, 2008).
leukemia (3 papers, 2019 to 2025). A malignant (clonal) hematologic disorder, involving hematopoietic stem cells and characterized by the presence of primitive or atypical myeloid or lymphoid cells in the bone marrow and the blood. "In this study, the authors show that ablation of Zc3h12a (which encodes Regnase-1) in CD8+ T cells improved the therapeutic efficacy of adoptively transferred, tumor-specific cells in mouse models of melanoma and leukemia." (PMID 34017005, 2021).
renal cell carcinoma (3 papers, 2019 to 2022). "Likely for the same reason, our results show that ZC3H12A is not the negative regulation of the proinflammatory cytokines (i.e., IL6, IL8) in CRC, different from what was reported in renal cell carcinoma." (PMID 31106233, 2019).
silicosis (3 papers, 2016 to 2021). Silicosis is a respiratory disease caused by breathing in (inhaling) silica dust. "CircHECTD1 controls fibroblast migration and proliferation by regulating its host gene HECTD1 in silicosis, which mediates ZC3H12A ubiquitination." (PMID 33533071, 2021). "Interestingly, circZC3H4, which is transcribed from ZC3H4, plays a similar role to circHECTD1 in silicosis, possibly because ZC3H4 and ZC3H12A belong to the family of CCCH‐typezinc finger proteins." (PMID 33533071, 2021).
ulcerative colitis (3 papers, 2020 to 2024). An inflammatory bowel disease involving the mucosal surface of the large intestine and rectum. "Additionally, gain-of-function mutations in the ZC3H12A gene (encoding Regnase-1) have been identified in intestinal epithelial cells of ulcerative colitis patients." (PMID 38491500, 2024). "Mutations of ZC3H12A had recently been verified to be associated with ulcerative colitis recently." (PMID 33043022, 2020).
colitis (2 papers, 2020 to 2023). Inflammation of the colon. "Our findings of enrichment of mutations in PIGR, ZC3H12A, and in the IL-17 and TLR pathways suggest there are distinct selection mechanisms in the colitis-affected colon, and somatic mutations potentially play a causal role in the pathogenesis of IBD." (PMID 32697969, 2020).
pulmonary arterial hypertension (2 papers, 2023 to 2024). Pulmonary arterial hypertension (PAH) is a group of diseases characterized by mean pulmonary artery pressure >20 mmHg and elevated pulmonary arterial resistance leading to right heart failure. "ZC3H12A deficiency in mouse alveolar macrophages represented severe pulmonary arterial hypertension, while IL-6 and IL-1β may have served as potential targets for ZC3H12A in alveolar macrophages." (PMID 37504305, 2023).
alcoholic hepatitis (1 paper, 2024). Acute hepatitis resulting from ingestion of alcohol. "Analysis of another data set provided by Hyun et al21 demonstrated that the expression of ZC3H12A is also induced in the livers of patients suffering from severe alcoholic hepatitis (AH)." (PMID 38311169, 2024).
dermatitis (1 paper, 2024). An inflammatory process affecting the skin. "This demonstrated that Tcf4 negatively regulated Il17c and Zc3h12a in vivo to promote skin inflammation." (PMID 38470486, 2024). "ZC3H12A/Regnase-1 has been previously shown to suppress imiquimod-elicited skin inflammation by regulating IL-17A and IL-17C responses." (PMID 38470486, 2024). "Finally, Zc3h12a expression correlated with measures of skin inflammation, such that Zc3h12a increased in KC-Tie2 mice compared with control animals and decreased in the absence of Il17c, Il17re, and Il17ra." (PMID 38470486, 2024). "Moreover, interference with cutaneous TCF4 using topical application of Tcf4 siRNA worsens skin inflammation by increasing cutaneous Il17c and Zc3h12a and by increasing skin infiltrating CD3+ T cell numbers, resulting in worsened acanthosis." (PMID 38470486, 2024). "A negative TCF4/IL-17C/ TNF-a/ IL-17A feedback loop decreases TCF4 in an IL-17RA/RE-dependent manner and is further amplified by IL-17C/TCF4 regulation of ZC3H12A and IL-17C regulation of NFKBIZ, resulting in self-sustaining skin inflammation." (PMID 38470486, 2024). "This loop is further amplified by IL-17C–TCF4 autocrine regulation of ZC3H12A and IL-17C regulation of NFKBIZ to promote self-sustaining skin inflammation." (PMID 38470486, 2024).
HIV-1 infection (1 paper, 2020). The type species of lentivirus and the etiologic agent of acquired immunodeficiency syndrome (AIDS). "Future studies of the susceptibility of PBMC of HIC to HIV-1 infection in vitro should analyze the potential role of both CDKN1A/p21 and ZC3H12A/MCPIP1 simultaneously." (PMID 32615986, 2020). "Increased expression of CDKN1A/p21 and ZC3H12A/MCPIP1 associated with T cell and/or monocyte activation may be a distinctive homoeostatic response to limit the deleterious effects of aberrant chronic immune activation and inflammation-driven by HIV-1 infection." (PMID 32615986, 2020). "Selective upregulation of ZC3H12A/MCPIP1 and CDKN1A/p21 may also play a crucial role in the control of HIV-1 infection by indirect mechanisms." (PMID 32615986, 2020). "This evidence prompted us to ask whether the expression of ZC3H12A/MCPIP1 could be elevated and positively correlated with CDKN1A/p21 in the setting of natural control of HIV-1 infection." (PMID 32615986, 2020).
Klebsiella pneumoniae (1 paper, 2025). "Although the absence of ZC3H12A in infectious diseases may exacerbate autoimmune responses, it may impair host defense in some infections; for example, ZC3H12A knockout enhances type I interferon responses and improves bacterial clearance in Klebsiella pneumoniae (KP) infection." (PMID 41154702, 2025).
mastitis (1 paper, 2018). Inflammation of breast tissue during lactation or postpartum due to an obstructed duct or infection. "We did detect, however, a moderate but significant upregulation of ZC3H12A (FC = +1.2, p = 0.039) when comparing mastitis vs. healthy human samples." (PMID 30271395, 2018).
nephritis (1 paper, 2021). Inflammation of renal tissue. "Thus, the increased nephritis in Zc3h12a+/– could be due to enhanced IL-17 production from T cells or to unrestrained IL-17 signaling in responder cells — or potentially both." (PMID 34236049, 2021).
papilloma (1 paper, 2024). A benign epithelial neoplasm that projects above the surrounding epithelial surface and consists of villous or arborescent outgrowths of fibrovascular stroma. "As expected, the level of Zc3h12a mRNA was almost completely decreased in the papillomas of the keratinocyte-specific Mcpip1 knockout mice compared to the control ones." (PMID 39428471, 2024).